MX2 (MX dynamin like GTPase 2)
Diseases named in the same sentence as MX2 in open-access papers (continued):
Sharing a sentence is not in itself a finding about the gene and the disease.
tumor (25 papers, 2005 to 2025). "However, further research investigating the associations of IRF4 rs12203592, CCND1 rs1485993, TERT rs2242652, and MX2 rs45430 with underlying biologic pathways related to tumor progression is warranted." (PMID 34898573, 2021). "We also observed increased expression levels of immune‐related genes, such as SLAMF7, TNFSF8, BTN3A1, CD2, LGALS9, PRF1, and MX2, in tumor samples from the MT group of the Local‐SCLC cohort." (PMID 38125769, 2023). "Ultimately, MX2 was identified for further analysis, including expression pattern, prognosis role, biological investigation, tumor microenvironment, immunotherapy evaluation and in vitro experiments validation." (PMID 37063301, 2023). "Next, we explored the possible effects of Mx2 depletion on those tumor cell lines in which the Mx2 mRNA levels are higher than 10% of that in A172 cells." (PMID 34707174, 2021). "This is the first time to demonstrate that Mx2 can also indirectly affect HSV-1 infection via interfering with the intrinsic expression of immune effector in tumor cells." (PMID 34707174, 2021). "On the other hand, the ability of the ovine IFN-τ to induce the expression of MHC class I and MX2 in the HPV 16 positive tumor cells is very important." (PMID 32626522, 2020). "As a result, MX2 is considered a candidate antitumour drug against multidrug resistant tumour cells." (PMID 15798770, 2005). "The significant upregulation of MX2 in high-risk patients, along with the reduced expression of FAM50B, FUCA1, AKAP6, and FCER1A in this group, further supports their potential roles in tumour progression and immune regulation." (PMID 40329678, 2025). "Previous studies also reported that IFI44L, TRIM22, OAS1, OAS2, and MX2 inhibited tumor proliferation and metastasis, indicating that the transcriptional regulation of STAT1/2 could limit the development of OS." (PMID 40956299, 2025). "Finally, we experimentally verified the differential expression of LAMP3 in UCEC and normal tissues, its effect on tumor cell invasion and migration ability, and its effect on the expression of the MX2 and STAT1." (PMID 38217544, 2024). "Our results indicate that MX2 may complete the remodeling of the tumor microenvironment by affecting the infiltration level of these cells and then play its biological role." (PMID 37063301, 2023). "Here we wonder whether Mx2 is a general restrictive factor of oHSV-1 virus multiplication in resistant tumor cell lines, possibly be taken as a candidate of biomarkers to predict the efficiency of oHSV-1 replication in tumors and oncolytic activity." (PMID 34707174, 2021). "Mx2 knockdown efficiency in indicated tumor cells were investigated by RT-qPCR." (PMID 34707174, 2021). "In this report, we sought to understand the comprehensive roles of Mx2 in tumor resistance to oHSV-1 infection, evaluating whether Mx2 depletion could reduce constitutive antiviral response to promote viral propagation in the resistant tumor cells." (PMID 34707174, 2021). "Metronomic CPA treatment also induced a core set of death-related genes that may be important for innate and/or adaptive immune activation by damaged tumor cells, including Sp110, Mx1, Mx2, Ebi3, Eomes, Tnfsf4, Gdf15, Ddx58, and Dhx58." (PMID 25952672, 2015). "Moreover, MX2 could decrease the sensitivity of tumor cells to sunitinib probably through PTEN/Akt pathway." (PMID 34306023, 2021). "For example, the elevated expression of MX2 and BIRC5 in CD8+ T cells indicates their potential to enhance T cell-mediated cytotoxicity, which is crucial for anti-tumor immunity." (PMID 40243888, 2025). "It was also shown that tumor cells alone can modulate the gene expression profile of naïve MSCs, including IL-6, BST2, ADAMTS12, MX2, LOXL2 and GREM1." (PMID 34513701, 2021).
tumor (continued). "The results obtained significantly expand knowledge on the anti-cancer effect of furanocoumarins and their effect on the induction of apoptosis in derived tumor cell lines from the human hematopoietic system: HL60, HL60/MX1 and HL60/MX2." (PMID 31083598, 2019). "MX2 has thus been capable of antitumour effects superior to those of adriamycin (ADM) against several murine and human tumour cell lines, even against multidrug-resistance tumour cell lines that overexpress P-glycoprotein." (PMID 15798770, 2005). "In addition, the expression of CCR4, MX2, and NR3C2 were significantly correlated with the stromal score, immune score, ESTTIMATE score, and tumor purity." (PMID 35619698, 2022). "We then analyzed tumor-infiltrating CD4 T cells and found an increased expression of interferon-beta (Ifnb1) and interferon-stimulated gene (ISG) transcripts (Ccl5, Ifit1, and Mx2) in cells isolated from mice treated with cGAMP compared with controls." (PMID 35091453, 2022). "In particular, IL6 and BST2 were significantly induced in all naïve MSCs after 3 days’ coculture with primary tumor cells, whereas the expressions of ADAMTS12, MX2, LOXL2 and GREM1 varied and displayed transient induction during the course of the coculture assay." (PMID 34513701, 2021). "Addition of TGF-β to tumor cell-N-MSC co-culture augmented MX2, BST2 and IL6 (right columns) but not ADAMTS12, LOXL2 GREM1 or CHI3L1 expression in N-MSCs." (PMID 29503225, 2018). "A previous study indicated that MX2 plays an important role in innate immunity against HIV-1, suggesting that MX2 might produce a marked effect by regulating anti−tumor immunity without directly affecting tumor cells in CRC." (PMID 38297270, 2024). "These indicate that Mx2 may not be a universal factor responsible for the resistance of tumor cells to oHSV-1 infection in a broad sense, while there might be a certain threshold of Mx2 accumulation." (PMID 34707174, 2021).
cancer (13 papers, 2019 to 2025). A tumor composed of atypical neoplastic, often pleomorphic cells that invade other tissues. "Nevertheless, in comparison with mature studies on the HIV-1 restriction function and antiviral effect of MX2, seldom do studies discuss its role in cancers." (PMID 34306023, 2021). "Those 6 genes in the model (PDK4, MPP1, ASGR1, MS4A14, FCER1A and MX2), rarely reported in cancers, were found to be significantly related to the prognostic survival of KIRC patients." (PMID 34606472, 2021). "Results showed that MX2 was differentially expressed in most cancer." (PMID 37063301, 2023). "Next, we evaluated the expression pattern of MX2 in pan-cancer." (PMID 37063301, 2023). "Hypo-methylated gDMs like MX2, OAS2, SPRED2, ADAP1, and SLC17A9 genes showed significant increased expression in cancer stage IV compared to stage I." (PMID 36329447, 2022). "Up-regulated expressions of the hypo-methylated gDMs in cancer were observed for OAS2, MX2, APOL3, ABHD8, RASSF1, SIGIRR, and SPRED2." (PMID 36329447, 2022).
Bacterial infection (2 papers, 2023). "Bacterial infection significantly upregulated mRNA expression levels of Isg15, Mx1, Mx2, Irf-3, Irf-7, Tlr-2, Tnf-α, Cxcl-1, and Il-6 genes." (PMID 37929187, 2023). "Variable selection using FS-PLS identified 4 genes distinguishing MIS-C from KD, viral and bacterial infections: HSPB1 Associated Protein 1 (HSPBAP1), Vacuolar Protein Sorting-Associated Protein 37C (VPS37C), Transforming Growth Factor Beta 1 (TGFB1) and MX Dynamin Like GTPase 2 (MX2)." (PMID 37255317, 2023).
immune dysfunction (2 papers, 2023). "Meanwhile, patients with higher MX2 expression might have a higher level of immune dysfunction, immune exclusion and CAF, while a lower level of MDSC and TAM M2." (PMID 37063301, 2023).
neurological disorders (1 paper, 2022). "Indeed, identified genes are implicated in viral (SEC14L1, JMJD6, SRSF2, TMPRSS2, MX1, MX2) bacterial (COL8A1, SPIRE1), and neurological disorders (MFSD11, METTL23, CTTNBP2, BACE2, IMPA2, MPPE1 and GNAL), or in the functions of the Golgi complex (MGAT5B), organelle where viral envelope is occurred." (PMID 35581286, 2022).
MX2 also shares sentences with these, for which no sentence is quoted: dengue (3 papers); liver cirrhosis (2); lupus (2); nevus (2); asthma (1); autoimmune (1); bovine respiratory disease complex (1); breast tumour (1); bronchiectasis (1); bronchitis (1); Clear Cell Renal Cell Carcinoma (1); cystic fibrosis (1); diabetes mellitus (1); Emphysema (1); genitourinary cancers (1); Hepatitis (1); hepatitis C (1); hepatoma (1); hypertensive disease (1); Immunodeficiency (1); inflammatory bowel disease (1); Inflammatory Myopathies (1); ischemia (1); kidney cancer (1); lentivirus infection (1); leukocytosis (1); lung carcinoma (1); lung diseases (1); lung neoplasm (1); malaria (1).
A further 18 diseases each share a sentence with MX2 in 1 paper.